NLRP3 (NLR family pyrin domain containing 3)
Diseases named in the same sentence as NLRP3 in open-access papers (continued):
Sharing a sentence is not in itself a finding about the gene and the disease.
depression (continued). "Moreover, it could ameliorate cognitive dysfunction and depression-like behaviors of db/db mice through the inhibition of ER stress and NLRP3 inflammasome activation." (PMID 30544722, 2018). "Here in this review, the roles of the NLRP3 inflammasome in the pathogenesis and progression of several well-known CNS diseases would be discussed, including cerebrovascular diseases, neurodegenerative diseases, multiple sclerosis, depression as well as other CNS disorders." (PMID 30233319, 2018). "Furthermore, in LPS or chronic stress-induced rodent models of depression, rodents displayed depressive-like behavior and activation of NLRP3 inflammasome in some brain areas such as the hippocampus, which were decreased after standard antidepressant medications." (PMID 29946236, 2018). "We suggest that decrease in BDNF by the activated NLRP3 inflammasomes in astrocytes is the key pathological event of the depressive-like behaviors induced by SD, while the combined treatment with fluoxetine and leptin improves therapeutic outcome for the depression induced by SD." (PMID 30666218, 2018). "In addition, it seems that NLRP3 inflammasome and IL-1β also play pivotal roles in depression." (PMID 29084550, 2017). "The activation of P2X7R and subsequent NLRP3 inflammasome in hippocampal microglial cells could mediate depressive-like behaviors, which suggests a new therapeutic target for the prevention and treatment of depression." (PMID 28486969, 2017). "Collectively, these data suggest that autophagy may interact with NLRP3 activation to contribute to the development of depression, whereas SalB can promote autophagy and induce the clearance of NLRP3, thereby resulting in neuroprotective and antidepressant actions." (PMID 29212498, 2017). "Therefore, scholars across the world postulated that therapies targeting the NLRP3 inflammasome might be a novel strategy for depression." (PMID 29084550, 2017). "Elevated protein and mRNA expression of NLRP3 and ASC have been reported in postmortem brain tissue from patients with depression." (PMID 41535967, 2026). "These cytokines influence depression-related pathophysiology by activating innate immune signaling pathways, including TLR4, NF-κB, MAPK, and the NLRP3 inflammasome, while also reshaping tryptophan-kynurenine metabolism through IDO1 and TDO2." (PMID 42212166, 2026). "AIH patients with depression, mice colonized with MDD microbiota, and ConA‐treated mice subjected to CUMS exhibit intestinal barrier dysfunction and hepatic NLRP3 inflammasome overactivation." (PMID 41503678, 2026). "Patients with major depressive disorder (MDD) display elevated serum levels of IL‐1β and IL‐18, accompanied by increased expression of the NLRP3 inflammasome and caspase‐1." (PMID 41556446, 2026). "We assessed airway inflammation, lung function, anxiety- and depression-like behaviors, gut microbiota composition, short-chain fatty acid (SCFA) levels, and the MAPK/P65/NLRP3 signaling pathway in the hippocampus and BV2 microglial cells." (PMID 41890764, 2026). "preclinical studies have shown that Yangxin decoction alleviates depression-like behaviors in CUMS-induced rats, potentially by inhibiting hippocampal neuronal apoptosis and inflammatory responses via the TLR4/NLRP3 signaling pathway." (PMID 41189264, 2025). "As an essential component of the innate immune system, the NLRP3 inflammasome exhibits excessive activation in both CVD and depression." (PMID 41194915, 2025). "In depression‐like mice, microglial NOD‐, LRR‐, and pyrin domain‐containing 3 (NLRP3) ablation mitigated A1‐like astrocyte induction." (PMID 39801259, 2025). "Research indicates that upon the activation of NLRP3, factors such as GSDMD, IL-1β, and IL-18 collectively contribute to the pathogenesis of depression." (PMID 41194915, 2025). "In preclinical studies, MOOs alleviate depression-like behaviors in PSD rats, mainly by regulating the NLRP3 inflammasome in microglia." (PMID 40936908, 2025).
depression (continued). "In the inflammatory response accompanying the onset of depression, TLR4, indoleamine 2,3-dioxygenase (IDO) and NLRP3 play important roles, with activation of NLRP3 inflammasome being more critical." (PMID 41179813, 2025). "Inhibition of key inflammatory pathways such as P2X7R/NLRP3 and NF-κB signaling pathways, regulation of hypothalamic–pituitary–adrenal axis (HPA axis) function, and tryptophan metabolism improved depression-like behavior in rodent models." (PMID 40033393, 2025). "The expression level of the 5-HT1A, DRD1, ADRA-2A, GABA-A α1, CNR1, NR3C2, NOD1, NLRP3 and MC4R; BDNF levels, glial activity and intestinal permeability were determined in chronic stress-induced depression in rats." (PMID 40281288, 2025). "Moreover, increasing studies showed that normal functional microglia autophagy can inhibit NLRP3 inflammasome activity to modulate neuroinflammation, and impairment of microglia autophagy leads to connive excessive NLRP3 inflammasome activation to induce depression-like behaviors." (PMID 40275171, 2025). "To summarise, the present study further supports that LPS-activated inflammasomes accelerate neuroinflammation and lead to depression by triggering PPARγ/CX3CR1/Nrf2 and the NF-κB/NLRP3 signaling pathways." (PMID 40308754, 2025). "BAs modulate depression pathogenesis through FXR, LXRs, and TGR5 receptors, orchestrating neuroinflammation (via NF-κB/NLRP3 suppression), gut microbiota metabolism (via GLP-1/FGF19 regulation), and neural plasticity (via BDNF/CREB activation)." (PMID 40362260, 2025). "In depression, arctiin can bind to P2X7R to exert neuroprotective effects, thereby inhibiting the P2X7R/NLRP3 inflammasome signaling pathway." (PMID 40936908, 2025). "In the brains of suicidal patients with depression, upregulation of NOD-like receptor family pyrin domain containing 3 (NLRP3) inflammasome expression has been observed." (PMID 40936908, 2025). "In psychiatric disorders such as depression, AC exhibits antidepressant potential, possibly through suppression of SIRT3/ROS‐mediated NLRP3 inflammasome activation." (PMID 40965425, 2025). "Hesperidin (20, 50, and 100 mg/kg orally for 28 days) reduces depression-like behaviors and expression of IL-1β, IL-6, TNF-α, NLRP3, caspase-1 in the prefrontal cortex and microglia in chronic unpredictable mild stress (CUMS)-induced rats." (PMID 40703750, 2025). "NLRP3 inflammasome, microglia, TNF-α, and brain-derived neurotrophic factor (BDNF) were the basis of neuroinflammation in depression." (PMID 40520890, 2025). "This study highlights the critical role of lncRNA Six3os1 in the pathological mechanisms of depression, demonstrating that it positively regulates COL9A3 by suppressing miR‐511‐3p, thereby modulating the MAPK/NLRP3 signaling axis." (PMID 41341504, 2025). "In depression, rats exposed to CUMS exhibit upregulation of the P2X7R/NLRP3/IL-1β signaling axis and display depression-like behaviors." (PMID 40936908, 2025). "In a word, this study indicates that PF can effectively alleviate the depression-like behavior of CUMS mice, which depends on the SIRT1 signal to regulate the activation of NLRP3 inflammasome and pyroptosis." (PMID 39684254, 2024). "PSP demonstrated inhibitory effects on the upregulation of NLRP3, ASC, caspase-1, cleaved-caspase-1, and IL-1β in LPS-induced depression model in mice." (PMID 38389919, 2024). "The total alkaloids of Fibraurea recisa activate the BDNF-MEK/ERK neuroprotective pathway and inhibit the NLRP3/caspase-1 inflammatory signaling pathway, alleviating CUMS-induced depression behavior in mice." (PMID 38643466, 2024). "So, NAR and NAR-HNPs reduced DM-induced depression by influencing brain neurotransmitters and exhibiting anti-oxidant and anti-inflammatory effects through the activation PPAR-γ/ NLRP3 pathway." (PMID 38866877, 2024).
depression (continued). "The present study evaluated the pharmacological effects of RGLS on depression-like behavior in ICV-STZ rats and explored related mechanisms from the perspective of NF-κB/NLRP3-mediated neuroinflammation and neuroplasticity." (PMID 38720779, 2024). "In this respect, this study investigates the mechanism by which PSP improves depression by inhibiting the TLR4 and NLRP3/ASC/caspase-1 signaling pathway in prefrontal cortex microglia using a chronic restraint stress (CRS) model." (PMID 39204578, 2024). "Baicalin inhibits microglia activation by regulating the NLRP3, AKT1, and S1RT1-NF-κB signaling pathways and consequently alleviates neuroinflammation and depression." (PMID 37764277, 2023). "SGB increases cerebral blood flow to suppress HIF-1α/NLRP3 inflammatory signaling, improving the CPSP and comorbid anxiety and depression." (PMID 36944982, 2023). "The results demonstrated that the mRNA and protein expression levels of NF‐κB and NLRP3 were significantly increased in CUMS‐induced depression‐like mice compared with the control group." (PMID 37408379, 2023). "Enhanced NLRP3 expression was detected in the hippocampal DG and CA1 subregions as well as the prefrontal cortex in CORT-induced depression mice." (PMID 36859349, 2023). "Therefore, blocking the activated NLRP3 inflammasome may be beneficial for treating depression." (PMID 36909194, 2023). "We next inhibited HIF-1α and NLRP3 by intra-thalamic injection of YC-1 (HIF-1α inhibitor) and MCC950 (NLRP3 inhibitor) and assessed mechanical pain sensitivity and anxiety- and depression-like behaviors." (PMID 36944982, 2023). "Our study showed that HIF-1α/NLRP3 inflammatory signaling contributed to the CPSP and comorbid anxiety and depression." (PMID 36944982, 2023). "NLRs consist of NLRP1, NLRP2, NLRP3, NLRP6, NLRC4, and NLRP12, of which NLRP3 has received the most attention in studies of the pathological mechanism of depression." (PMID 37881439, 2023). "Inhibiting thalamic HIF-1α/NLRP3 signaling prevented thalamic hemorrhage stroke-induced CPSP, anxiety, depression, and peri-thalamic lesion site neuroinflammation." (PMID 36944982, 2023). "In the depression model, SIRT3 can reduce ROS and activate NF-kB signals in the hippocampus of mice, thereby alleviating NLRP3-induced pyroptosis." (PMID 38044382, 2023). "All these results suggest that inhibiting HIF-1α and NLRP3 prevented CPSP-related anxiety and depression." (PMID 36944982, 2023). "XYS is proven a safe and effective treatment or adjuvant therapy for depression, which could regulated necroptosis, alleviates hippocampal glutamate-induced toxicity, regulating autophagy in hypothalamic neuron, modulated the gut microbiota and regulating the NLRP3 inflammasome." (PMID 37322430, 2023). "Higher levels of IL-6, NLRP3, and TNF- α predicted a better response to ECT in patients with treatment-resistant depression." (PMID 37699900, 2023). "In conclusion, these findings suggested that depression-like behaviors induced by CUMS stimulation were related to altered gut microbiota, broke the intestinal barrier, promoted the expression of NLRP3 inflammasome and elevated inflammation." (PMID 37293210, 2023). "Many types of neurological diseases are related to neuroinflammation mediated by the NLRP3 inflammasome, such as AD, PD, amyotrophic lateral sclerosis (ALS), multiple sclerosis (MS), and depression." (PMID 36838564, 2023). "In CNS diseases animal models, such as AD, VA, depression, stroke and SCI, acupuncture regulated the NLRP3 inflammasome activation with the characteristics of multiple targets, multiple links and multiple pathways." (PMID 36925735, 2023). "Some studies have shown that NLRP3 inflammasome is activated in some other brain regions in LPS- and CUMS-induced depression models." (PMID 37626978, 2023). "Thus, since the NLRP3 inflammasome is one of the key players in the interactions between microglia and neurotoxic A1 astrocytes, it may serve as a target for the treatment of depression." (PMID 36675113, 2023).
depression (continued). "We found that HIF-1α/NLRP3 signaling was critical for the development of CPSP and its related anxiety and depression." (PMID 36944982, 2023). "In a different study using a post-stroke depression model, physical exercise was also shown to block the TLR4/NF-kB/NLRP3 signaling pathway in the mouse hippocampus through inhibition of the phosphatase and tensin homologue (PTEN)." (PMID 36613574, 2022). "NLRP3, caspase-1, ASC, IL-6, and IL-1β in this signaling pathway are closely related to inflammation and depression." (PMID 36556951, 2022). "ERS has been reported to induce NLRP3 inflammasome activation in different cell types, and the interaction between ERS, NLRP3 inflammasome, and inflammation promotes the development of depression." (PMID 36353576, 2022). "In fact, the downstream cytokines of NLRP3, including IL-1β and TNF-α, were increased in the cerebral spinal fluid and serum of patients with depression." (PMID 36187801, 2022). "It proved that AFR has therapeutic effects on depression by verifying the BDNF-MEK signalling pathway and NLRP3/caspase-1 inflammatory signalling pathway in vitro and in vivo." (PMID 35938494, 2022). "The gut microbiota of NLRP3 KO mice transplanted into chronic unpredictable stress (CUS) mice modulated astrocyte dysfunction and improved depression-like behavior in CUS mice via circHIPK2." (PMID 35431783, 2022). "Subsequently, the effects of SJE on alleviating depression and anxiety by inflammatory response were investigated by measuring the expression levels of inflammatory cytokines and key proteins in TLR4/NLRP3 signaling pathways." (PMID 34977127, 2021). "Thus, targeting the NLRP3 inflammasome may be a new approach for treating depression." (PMID 33935710, 2021). "Our results showed that the expression levels of TLR4, MyD88, NF-κB-p65, TAK1, IRAK1, TRAF6, inflammasome-related NLRP3, ASC, and caspase-1 were all increased in rats of the depression model group." (PMID 33505499, 2021). "In this study, we used colonic tissue to study depression and investigated key factors involved in the TLR4/NLRP3 inflammasome signaling pathway by H&E staining, immunohistochemistry, qPCR, and Western blotting." (PMID 33505499, 2021). "Lipopolysaccharide and chronic social defeat stress models of depression were established to examine the impact of isoliquiritin on depressive behaviors, hippocampal miRNA-27a/SYK/NF-κB cascade and NLRP3-regulated pyroptosis." (PMID 33402173, 2021). "Following identification of elevated IL-1β, IL-6, and TNF-α levels in the pathophysiology of major depressive disorder, the interaction of BHB with NLRP3 inflammasome was probed in a relevant murine model of this disorder." (PMID 34443594, 2021). "Curcumin, an IDO-1 inhibitor, suppresses NLRP3 expression in chronic unpredictable mild stress (CUMS) and reduces depression-like behaviors." (PMID 34735466, 2021). "Therefore, the NLRP3 inflammasome may become a new target for improving depression in the future." (PMID 34526897, 2021). "The Ban-Xia-Hou-Pu decoction plays an antidepressant role by inhibiting the activation of NLRP3 inflammasomes and the production of IL-1β in the liver, hypothalamus, hippocampus, or prefrontal cortex of CUMS-induced depression rats." (PMID 33790789, 2021). "Ori may alleviate LPS-induced depression by inhibiting NLRP3 inflammasome through activation of autophagy both in the hippocampus of the LPS-induced depression model mice and LPS-treated astrocytes, which unveiled the new protective mechanism of Ori treatment in depression." (PMID 35096901, 2021). "Clinical evidence demonstrated that the concentrations of NLRP3 activated cytokines such as IL-1β, IL-6, and TNF-α were elevated in the cerebral spinal fluid (CSF) and serum of patients with depression." (PMID 33402173, 2021).
depression (continued). "Inflammation is now known to be involved in the pathophysiology of depression, and BHB administration can induce antidepressant effects by suppressing NLRP3, a critical complex that senses stress molecules and mediates inflammatory responses." (PMID 32125791, 2020). "Thus, NLRP3 may be a key component that mediates inflammation in depression." (PMID 32125791, 2020). "The pathogenesis of depression is closely related to neuroinflammation, and the anti-inflammatory activity of TCA is related to its inhibition of the activation of NLRP3 inflammasome." (PMID 32328132, 2020). "The key mechanism is the inflammatory response triggered by the Nrf2/NLRP3 signaling pathway, which has been demonstrated in the study of PM2.5 pollution-induced depression." (PMID 32166013, 2020). "Herein, we summarize the effect of the NLRP3 inflammasome and P2X7 receptor in DM and depression, respectively, and deduce their pathological roles in DD." (PMID 32166013, 2020). "The expression of NF-κB was blocked by NLRP3 inhibitor MCC950 and NLRP3 gene knockout, in the model of inflammatory hyperalgesia and chronic unpredictable mild stress (CUMS) induced depression, respectively." (PMID 30635040, 2019). "The results from our and others' studies indicate the activation of the NF-κB pathway and NLRP3 inflammasome in brain regions prefrontal cortex and hippocampus in rodents of CUMS-induced depression, which are consistent with the reports in depressed patients." (PMID 29853787, 2018). "Treatment of db/db mice with NLRP3 inflammasome inhibitor MCC950 ameliorated anxiety- and depression-like behaviors as well as cognitive dysfunction, and reversed increased NLRP3, ASC, and IL-1βexpression levels and caspase-1 activity in hippocampus." (PMID 29495433, 2018). "In addition, recently, researches exhibited that NLRP3 inflammasome is activated in depressed animal models and in depressive patients as well, which suggests that NLRP3 inflammasome might be a new target and offer new perspectives in the study of depression." (PMID 28486969, 2017). "The NLRP3 inflammasome, involved in CASP1 activation, exerts a crucial effect on depression." (PMID 41503678, 2026). "Compared with nondepressed AIH patients, those with depression showed exacerbated intestinal barrier dysfunction and hepatic NLR family pyrin domain containing 3 (NLRP3) inflammasome overactivation." (PMID 41503678, 2026). "Therefore, regulating and intervening in the activation of the NLRP3 inflammasome offers new avenues for treating CVD and depression comorbidity." (PMID 41194915, 2025). "Nonpharmacological treatments targeting the NLRP3 inflammasome, such as physical exercise, acupuncture, and electroacupuncture, have also demonstrated effectiveness in treating depression." (PMID 41194915, 2025). "In pathological contexts such as AD, PD, major depressive disorder (MDD), and intracerebral hemorrhage (ICH), microbiota-driven activation of NLRP3 promotes peripheral and central inflammation, compromises gut barrier integrity, and leads to white matter injury and neurodegeneration." (PMID 41007735, 2025). "JNW could alleviate depression-like behavior in mice subjected to CUMS, and these effects may be mediate through NF-κB/NLRP3 pathway." (PMID 40612748, 2025). "In this study, we evaluated the effects of DACA on depression‐like behavior in CUMS‐induced mice and explored whether its action is mediated by the inhibition of HMGB1/NF‐κB/NLRP3 signaling pathways, which are involved in neuroinflammation." (PMID 40406924, 2025). "Studies have found that activation of the NLRP3/caspase-1/Gasdermin D (GSDMD) pathway leads to pyroptosis of astrocytes in the hippocampus of chronically stressed mice, enhancing neuroinflammatory responses and mediating the onset of depression." (PMID 40699781, 2025).